MYC (MYC proto-oncogene, bHLH transcription factor)
Description:
Transcription factor that binds DNA in a non-specific manner, yet also specifically recognizes the core sequence 5'-CAC[GA]TG-3'. Activates the transcription of growth-related genes. Binds to the VEGFA promoter, promoting VEGFA production and subsequent sprouting angiogenesis. Regulator of somatic reprogramming, controls self-renewal of embryonic stem cells (By similarity). Functions with TAF6L to activate target gene expression through RNA polymerase II pause release (By similarity). Positively regulates transcription of HNRNPA1, HNRNPA2 and PTBP1 which in turn regulate splicing of pyruvate kinase PKM by binding repressively to sequences flanking PKM exon 9, inhibiting exon 9 inclusion and resulting in exon 10 inclusion and production of the PKM M2 isoform.
Synonyms: bHLHe39; c-Myc; MYCC; MRTL
Tractability: Small molecule: a structure with a bound ligand is known; a high-quality ligand is known. PROTAC: UniProt records ubiquitination sites on it; ubiquitination databases record sites on it; a small molecule that binds it is known.
Target class: Transcription factor
Gene: Protein-coding gene on chromosome 8 (127,735,434 to 127,742,951, forward strand). Ensembl gene ENSG00000136997.
Subcellular location: Nucleus, nucleoplasm; Nucleus, nucleolus; Nucleus; Cytoplasm; Chromosome
Subcellular location (Human Protein Atlas): Nucleoplasm
Pathways (Reactome):
Signal Transduction: Binding of TCF/LEF:CTNNB1 to target gene promoters; Ca2+ pathway; Estrogen-dependent gene expression; Formation of the beta-catenin:TCF transactivating complex; MAPK6/MAPK4 signaling; NOTCH1 Intracellular Domain Regulates Transcription; Repression of WNT target genes; SMAD2/SMAD3:SMAD4 heterotrimer regulates transcription; Signaling by ALK
Cell Cycle: Cyclin A:Cdk2-associated events at S phase entry; Cyclin E associated events during G1/S transition; Transcription of E2F targets under negative control by DREAM complex
Disease: Constitutive Signaling by NOTCH1 HD+PEST Domain Mutants; Constitutive Signaling by NOTCH1 PEST Domain Mutants
Gene expression (Transcription): RUNX3 regulates WNT signaling; TFAP2 (AP-2) family regulates transcription of cell cycle factors
Immune System: Interleukin-4 and Interleukin-13 signaling; Regulation of PD-L1(CD274) transcription
Cell-Cell communication: Regulation of CDH1 mRNA translation by microRNAs
Cellular responses to stimuli: Regulation of NFE2L2 gene expression
Developmental Biology: Transcriptional regulation of granulopoiesis
Metabolism of proteins: Ub-specific processing proteases
Gene Ontology:
Molecular function: core promoter sequence-specific DNA binding; DNA-binding transcription activator activity, RNA polymerase II-specific; DNA-binding transcription factor activity, RNA polymerase II-specific; DNA-binding transcription factor binding; DNA-binding transcription repressor activity, RNA polymerase II-specific; E-box binding; identical protein binding; protein binding; protein-containing complex binding; RNA polymerase II cis-regulatory region sequence-specific DNA binding; transcription coregulator binding; DNA binding; DNA-binding transcription factor activity; protein dimerization activity
Biological process: cellular response to hypoxia; cellular response to UV; cellular response to xenobiotic stimulus; chromatin remodeling; chromosome organization; DNA damage response; ERK1 and ERK2 cascade; G1/S transition of mitotic cell cycle; intracellular iron ion homeostasis; MAPK cascade; negative regulation of cell division; negative regulation of fibroblast proliferation; negative regulation of gene expression via chromosomal CpG island methylation; negative regulation of monocyte differentiation; negative regulation of transcription by RNA polymerase II; negative regulation of transcription initiation by RNA polymerase II; positive regulation of cell population proliferation; positive regulation of DNA-templated transcription; positive regulation of epithelial cell proliferation; positive regulation of fibroblast proliferation; positive regulation of gene expression; positive regulation of miRNA transcription; positive regulation of transcription by RNA polymerase II; protein-DNA complex disassembly; and 16 more
Cellular component: chromatin; chromosome; cytoplasm; Myc-Max complex; nucleolus; nucleoplasm; nucleus; protein-containing complex; RNA polymerase II transcription repressor complex
Genetic constraint (gnomAD): Loss-of-function variants: 1 observed, 37.14 expected, observed/expected ratio (o/e) 0.0269, 90% interval 0.009 to 0.13. The upper end of that interval is the gene's LOEUF score, 0.13, which puts it in group 1 of 6, group 1 being the genes least tolerant of losing a copy. Missense variants: 508 observed, 611.31 expected, observed/expected ratio (o/e) 0.83, 90% interval 0.77 to 0.89. Synonymous variants: 267 observed, 262.47 expected, observed/expected ratio (o/e) 1.02, 90% interval 0.92 to 1.13.
Cancer hallmarks: proliferative signalling (promotes); genome instability and mutations (promotes); angiogenesis (promotes); cell replicative immortality (suppresses); invasion and metastasis (suppresses); escaping programmed cell death (suppresses); change of cellular energetics (promotes); escaping immune response to cancer (promotes)
Homologues: Orthologues: chimpanzee MYC (99% identical), macaque MYC (97% identical), pig MYC (92% identical), rabbit MYC (91% identical), mouse Myc (90% identical), rat Myc (89% identical), guinea pig MYC (89% identical), tropical clawed frog myc (60% identical), zebrafish myca (54% identical), zebrafish mycb (54% identical). Paralogues in human: MYCN (39% identical), MYCL (28% identical).
Diseases named in the same sentence as MYC in open-access papers:
MYC is named in the same sentence as 780 diseases in open-access papers, as found by Europe PMC text mining. Sharing a sentence is not in itself a finding about the gene and the disease. The quoted sentences say what the papers report.
breast cancer (1,728 papers, 1995 to 2026). A primary or metastatic malignant neoplasm involving the breast. "One study used CROP-seq of MCF10A cells harbouring loss of PTEN, PIK3CA, or MYC oncogenic alterations for dual targeting of tumour suppressor genes to explore epistatic networks in breast cancer." (PMID 40650785, 2025). "Dysregulated MYC activity is a hallmark of various malignancies, including breast cancer, where it is linked to aggressive disease progression." (PMID 40710353, 2025). "Previous studies have linked elevated SCARB2 to tumor progression in breast cancer and liver cancer, where it regulates key pathways, such as MYC acetylation and tumor-infiltrating immune cell levels." (PMID 41210942, 2025). "So far, most of the studies have shown that FLT4 amplification primarily occurs in sAS, particularly those associated with radiation therapy for breast cancer or chronic lymphedema, and always in association with MYC amplification." (PMID 40666093, 2025). "We previously reported that GPS2 deletion in triple-negative MDA-MB231 breast cancer cells is associated with the upregulation of MYC and MYC-dependent target genes." (PMID 40305047, 2025). "Research has shown that the overexpression of MYC is associated with poorer prognosis and a greater risk of breast cancer." (PMID 40612865, 2025). "In breast cancer, amplification or overexpression of MYC has been associated with poor prognosis and resistance to a variety of systemic therapies including endocrine therapy, chemotherapy, CDK4/6 inhibitors, mTOR inhibitors, and immunotherapy." (PMID 39875774, 2025). "Altered MYC is implicated in various cancer types, including breast cancer, where it is associated with poorer outcomes (63, –65)." (PMID 40305047, 2025). "Another study exploring RNA-binding proteins identified YTHDF2 as a driver of cell death in MYC-driven breast cancer given that loss of YTHDF2-dependent mRNA degradation induces apoptosis in TNBC." (PMID 40650785, 2025). "Protein–protein interaction (STRING) analysis indicated that TGFB2 is associated with EGFR and MYC from the PAM50 breast cancer gene signature." (PMID 41373732, 2025). "The MYC pathway has been implicated in breast cancer progression and is associated with poor prognosis." (PMID 39207954, 2024). "In this study we find that GNA13 regulates the expression of MYC exclusively in ER+ breast cancer cells, and that the induction of MYC observed upon GNA13 loss is dependent on the expression and activation of ERα." (PMID 38965558, 2024). "MYC is a master regulator of cell growth and metabolism, and its dysregulation is a hallmark of many cancers, including breast cancer." (PMID 39596229, 2024). "Of note, univariate Cox-regression analysis of ER+/HER2− breast cancer samples from the HMF data showed that MYC amplification is significantly associated with everolimus-based treatment duration (HR = 2.70, P = 0.01)." (PMID 37642941, 2023). "We also showed that MYC status is significantly associated with clinical response to the mTORi everolimus in breast cancer patients, thus establishing MYC as a clinically significant driver of mTORi resistance." (PMID 37642941, 2023). "MYC is also regulated by the serine/threonine kinase PIM1 implicated in breast cancer development and progression, whose upregulation correlates with decreased patient survival and therapy resistance." (PMID 36969025, 2023).
breast cancer (continued). "The estrogen receptor, on the other hand, is the marker par excellence of the luminal subtypes; while germline or somatic mutations of the breast cancer susceptibility genes and MYC activation are frequent in the basal subtype." (PMID 37564937, 2023). "We identified a linear RNA motif-associated module to be prognostic in patients with breast cancer that harbor deep amplification of the MYC locus even after accounting for confounding clinical factors." (PMID 36950380, 2023). "Through correlative mass spectrometry imaging, we show that pantothenic acid (vitamin B5) associates with MYC-high areas within both human and murine mammary tumors, where its conversion to coenzyme A fuels Krebs cycle activity." (PMID 37946084, 2023). "Another example of nanotherapeutic delivery is the transport of a MYC inhibitor into tumor-associated macrophages in breast cancer." (PMID 36969025, 2023). "Amplification of the MYC oncogene occurs more frequently in TNBC tumors (~60%) than other breast cancer subtypes and is also associated with worse outcomes." (PMID 37704631, 2023). "Specifically, we find that both m6A deposition in splice site boundaries and in splicing and transcription factor transcripts, such as MYC, direct AS switches of specific breast cancer-associated transcripts." (PMID 36725888, 2023). "Among these factors, c-MYC has been extensively investigated and represents the most studied transcriptional activator associated with hTERT regulation in breast cancer." (PMID 37612721, 2023). "Considering the vital role of c-MYC in both breast cancer cells and TME, this review aimed to summarize the functions and underlying mechanisms of c-MYC acts in the communication between breast cancer cells and TME." (PMID 36721232, 2023). "FBXW9 was also strongly correlated with cancer cell stemness, and genes correlated with FBXW9 were associated with several MYC activities according to gene enrichment analysis in breast cancer." (PMID 36982338, 2023). "MYC is one of the most commonly mutated genes in breast cancer, showing a strong correlation with cell competition." (PMID 36624542, 2023). "For example, in breast cancer, MYC-driven epigenetic reprogramming causes activation of de novo enhancers to support dedifferentiation and onset of a stem-like state while repressing transcriptional activity of lineage-specifying transcription factors." (PMID 37345125, 2023). "Here, we show that genetic deletion of the gene encoding hepsin (Hpn) in a WAP-Myc model of aggressive MYC-driven breast cancer inhibits tumor growth in the primary syngrafted sites and the growth of disseminated tumors in the lungs." (PMID 37872868, 2023). "YEATS4 has been described as an oncogene in several cancer types, interacts directly with MYC and has been implicated in migration and invasion in breast cancer through regulation of miRNAs." (PMID 36860495, 2022). "Our study shows that in triple-negative and BRCA1/2-mutated breast cancer, MYC utilizes yet another strategy to promote immune evasion, namely by expulsion of virtually all tumor-infiltrating immune cell populations." (PMID 36323660, 2022). "The overexpression of c-MYC is implicated in resistance to endocrine therapy in ER+ve breast cancer." (PMID 35267559, 2022). "Taken together, our results show that MYC expression drives a dramatic loss of lymphocytic infiltration, as well as other immune cells, in mouse and human breast cancer." (PMID 36323660, 2022).
breast cancer (continued). "MYC deregulation contributes to breast cancer development and progression and is associated with poor outcomes." (PMID 35563727, 2022). "Since the effect of MYC overexpression on CD3+ TILs was most profound in the BRCA1-deficient mammary tumors, we further focused on the WB1P model." (PMID 36323660, 2022). "The expansion part consisted of patients with small-cell lung cancer, HER2-negative breast cancer, MYC-amplified/β-catenin-mutated (MT) tumours or other (basket cohort)." (PMID 33020594, 2021). "Cell proliferation-related pathways such as E2F targets, G2M checkpoint, and MYC target scores were significantly associated with the pathological grade in breast cancer." (PMID 33804148, 2021). "We further showed that echinomycin caused degradation of HIF1α and MYC in a variety of cancer types tested here, including lung cancer, breast cancer, lymphoma and leukemia." (PMID 33572152, 2021). "Though MYC is less commonly altered in breast cancer, it is a well‐known oncogene and has been associated with metastatic disease." (PMID 34159748, 2021). "PVT1 is a long noncoding RNA that is commonly overexpressed in breast cancer and has been implicated in the regulation of MYC oncogene, while JAK2 is a tyrosine kinase activating cancer-driving JAK/STAT signaling pathway." (PMID 34439480, 2021). "Acquired resistance to GDC-0941 in SUM-159 breast cancer cells was found to be associated with a focal amplification in the MYC locus and inhibition of BET with JQ1 sensitized resistant cells to GDC-0941 treatment." (PMID 33446653, 2021). "High MYC has been reported to be associated with a poor prognosis of prostate cancer and breast cancer." (PMID 34631699, 2021). "MYC is a major proto-oncogene in breast cancer, especially for HER2 and BRCA-1 associated cancers that have poor prognoses." (PMID 33996588, 2021). "Fourteen (35%) patients had stable disease (5 SCLC, 5 MYC-amp/B-cat mutation-positive tumours, 1 breast cancer and 2 basket cohort patients (1 mesothelioma, 1 colorectal cancer)." (PMID 33020594, 2021). "High expression of MYC and its downstream target genes is associated with tumor aggressiveness in human breast cancer." (PMID 34169837, 2021). "We have previously published that cell proliferation-related scores that are associated with patient survival including MYC, G2M checkpoint, and E2F target scores in breast cancer." (PMID 34503253, 2021). "Previous studies have applied the Shannon index for diagnostic purposes, for instance applying the genetic variability of c‐MYC to identify breast cancer patients at a higher risk of mortality." (PMID 34328665, 2021). "Contrastingly, a study has found that silencing the PVT1 promoter results in increased cell proliferation and competition in breast cancer cells, which was associated with an increase in MYC expression." (PMID 33499210, 2021). "This region is important because it is commonly amplified in breast cancer tumors associated with altered function of MYC." (PMID 32850369, 2020).